FADS3 (fatty acid desaturase 3)
Description:
Mammals have different sphingoid bases that differ in their length and/or pattern of desaturation and hydroxyl groups. The predominant sphingoid base that comprises mammalian ceramides is sphing-4-enine (sphingosine or SPH) which has a trans (E) desaturation at carbon 4. FADS3 is a desaturase that introduces a cis (Z) double bond between carbon 14 and carbon 15 of the sphingoid base (also known as long chain base, LCB), producing LCBs such as sphinga-4,14-dienine (SPD, d18:2(4E,14Z)) from SPH. Prefers SPH-containing ceramides (N-acylsphing-4-enines) as substrates. Capable of metabolizing also the SPH in its free form. SPD ceramides occur widely in mammalian tissues and cells. Due to their unusual structure containing a cis double bond, SPD ceramides may have an opposite, negative role in lipid microdomain formation relative to conventional ceramides. Could be involved in the detoxification of 1-deoxy sphingolipids, by desaturating the cytotoxic 1-deoxysphinganine (1-deoxySA, m18:0), produced under pathological conditions, to 1-deoxysphingenine (1-deoxysphingosine, 1-deoxySO, m18:1) (Probable). Although prefers SPH-containing ceramides (N-acylsphing-4-enines) as substrates, it also exhibits activity toward dihydrosphingosine-containing CERs (N-acylsphinganines) and produces 14Z-SPH-containing sphingolipids,which can be found in patients with DEGS1 mutations. Its desaturase mechanism involves an electron transfer facilitated by cytochrome b5. FADS3 also acts as a methyl-end fatty acyl coenzyme A (CoA) desaturase that introduces a cis double bond between the preexisting double bond and the terminal methyl group of the fatty acyl chain (By similarity). Desaturates (11E)-octadecenoate (trans-vaccenoate, the predominant trans fatty acid in human milk) at carbon 13 to generate (11E,13Z)- octadecadienoate (also known as conjugated linoleic acid 11E,13Z-CLA) (By similarity).
Synonyms: CYB5RP; LLCDL3
Tractability: Antibody: UniProt predicts a signal peptide or a membrane-spanning region. PROTAC: ubiquitination databases record sites on it; its protein half-life has been measured.
Gene: Protein-coding gene on chromosome 11 (61,873,519 to 61,892,136, reverse strand). Ensembl gene ENSG00000221968.
Subcellular location: Endoplasmic reticulum membrane
Subcellular location (Human Protein Atlas): Nucleoli fibrillar center
Gene Ontology:
Molecular function: protein binding; oxidoreductase activity
Biological process: unsaturated fatty acid biosynthetic process; lipid metabolic process; sphingolipid metabolic process
Cellular component: membrane; endoplasmic reticulum membrane
Genetic constraint (gnomAD): Loss-of-function variants: 30 observed, 55.98 expected, observed/expected ratio (o/e) 0.54, 90% interval 0.4 to 0.73. The upper end of that interval is the gene's LOEUF score, 0.73, which puts it in group 2 of 6, group 1 being the genes least tolerant of losing a copy. Missense variants: 432 observed, 562.02 expected, observed/expected ratio (o/e) 0.77, 90% interval 0.71 to 0.83. Synonymous variants: 234 observed, 228.87 expected, observed/expected ratio (o/e) 1.02, 90% interval 0.92 to 1.14.
Homologues: Orthologues: chimpanzee FADS3 (100% identical), macaque FADS3 (99% identical), pig FADS3 (90% identical), mouse Fads3 (90% identical), dog FADS3 (88% identical), rat Fads3 (87% identical), guinea pig FADS3 (82% identical), rabbit FADS3 (80% identical), tropical clawed frog fads2 (59% identical), zebrafish fads2 (55% identical), Caenorhabditis elegans fat-3 (28% identical), Caenorhabditis elegans fat-4 (27% identical). Paralogues in human: FADS2 (62% identical), FADS1 (52% identical), FADS6 (17% identical).
Diseases named in the same sentence as FADS3 in open-access papers:
FADS3 is named in the same sentence as 18 diseases in open-access papers, as found by Europe PMC text mining. Sharing a sentence is not in itself a finding about the gene and the disease. The quoted sentences say what the papers report.
breast carcinoma (2 papers, 2022 to 2024). "In breast cancer, FADS3 has been observed to enhance cell membrane fluidity and facilitate hematogenous diffusion and lung metastasis." (PMID 38660262, 2024). "FADS3 was also more expressed in CTC-enriched blood samples compared to tumor cell-enriched fine-needle biopsies in a group of breast cancer patients." (PMID 35216615, 2022). "Literature data on the role of FADS3 in breast cancer are still scanty, although evidence for an altered fatty acid transport, synthesis and desaturation was recently reported as responsible for breast cancer response to therapy, recurrence and plasticity." (PMID 35216615, 2022).
glioblastoma (1 paper, 2023). The most malignant astrocytic tumor (WHO grade IV). "However, FADS3 is one of the few fatty acid synthesis genes whose increased expression in glioblastoma tumors is associated with worse patient prognosis, according to the GEPIA portal." (PMID 37046844, 2023). "The expression of FADS3 in glioblastoma tumors does not differ from that of nontumor brain tissue." (PMID 37046844, 2023).
vitiligo (1 paper, 2025). Generalized well circumscribed patches of leukoderma that are generally distributed over symmetric body locations and is due to autoimmune destruction of melanocytes. "Additionally, we detected potential shared susceptibility genes between vitiligo and RA through SMR analyses, namely FCRL3, FADS1, and FADS3." (PMID 40468464, 2025).
tumor (5 papers, 2020 to 2026). "Bioinformatics analysis was also used to investigate the association of FADS3 expression with tumor progression, prognosis, TIME, and potential pathogenic mechanism in ccRCC." (PMID 42220493, 2026). "Fatty acid desaturase 3 (FADS3), a sphingoid Δ14Z desaturase, is required for the synthesis of unsaturated fatty acids in tumor biology." (PMID 42220493, 2026). "FADS3, as a member of the fatty acid desaturase family, has received increasing attention in tumor biology." (PMID 38660262, 2024). "In orthotopic xenograft models, the tumor masses of FADS3 knock-down and control mice were comparable, thus corroborating in vitro data." (PMID 35216615, 2022). "The expression of FADS3 measured against the GAPDH reference gene was higher in the growing tumor area versus the peritumoral area and in the necrotic core versus the peritumoral area, but again the differences were statistically insignificant." (PMID 32392704, 2020). "Patients who had a higher expression of the FADS3 gene in the tumor showed a lower 3-year survival (6%) than patients with a low expression of this gene (13%, p = 0.039)." (PMID 32392704, 2020). "At the same time, FADS3 expression in the peritumoral area negatively correlated with SCD5 expression in the growing tumor area." (PMID 32392704, 2020). "FADS3 was among the upregulated genes associated with lipid metabolism, which was expressed not only in ccRCC tumor cells but also in cells of the TIME, such as tumor-associated macrophages (TAMs)." (PMID 42220493, 2026). "We hypothesized that FADS3-overexpressing tumor cells have an increased membrane fluidity and motility." (PMID 35216615, 2022). "FADS3 expression measured against B2M reference gene was lower in the growing tumor area versus the peritumoral area and in the necrotic core versus the peritumoral area, but—similarly to previous genes—the observed differences were not statistically significant." (PMID 32392704, 2020). "Nevertheless, it is not possible to determine whether the sex-related difference in FADS3 in our study was due to a difference existing in healthy brains or the simultaneous effect of sex hormones and signal molecules secreted by the GBM tumor." (PMID 32392704, 2020). "Therefore, the aim of this study was to analyze the mRNA expression of desaturase genes—SCD, SCD5, FADS1, FADS2, and FADS3—in GBM in three tumor zones: necrotic core, growing tumor area, and peritumoral area." (PMID 32392704, 2020). "In this study we focused on the effect of fatty acid desaturation on membrane fluidity and demonstrated that CTCs exploit the enzymatic activity of FADS3 to increase their motility, with no influence on cell proliferation and tumor growth rate in MDA-MB-231 models." (PMID 35216615, 2022).
cancer (3 papers, 2020 to 2024). A tumor composed of atypical neoplastic, often pleomorphic cells that invade other tissues. "FADS3 encodes an enzyme that catalyzes double bond introduction into the fatty acid acyl chains (a chemical modification that determines the level of phospholipids packing), therefore regulating cell membrane fluidity and dissemination of cancer cells." (PMID 38660262, 2024).
metabolic disease (1 paper, 2023). A congenital disorder (due to inherited enzyme abnormality) or acquired (due to failure of a metabolically important organ) disorder resulting from an abnormal metabolic process. "FADS3 also inserts the Δ14Z double bond to 1-deoxySLs, non-canonical toxic forms of SLs found in inherited and metabolic disease conditions." (PMID 37890668, 2023).
FADS3 also shares sentences with these, for which no sentence is quoted: diabetes (2 papers); dyslipidemia (2); Atopic Dermatitis (1); cardiovascular disease (1); clear cell renal cell carcinoma (1); colon cancer (1); coronary artery disease (1); glioma (1); hyperlipidemia (1); migraines (1); nutritional deficiency (1); Obesity (1).